INS (insulin)
Diseases named in the same sentence as INS in open-access papers (continued):
Sharing a sentence is not in itself a finding about the gene and the disease.
pancreatitis (continued). "FRCs are not advised for patients lacking insulin secretion (proved by serum C-peptide level), advanced renal impairment (eGFR < 30 mL/min), pregnancy or breastfeeding, a history of pancreatitis, or known hypersensitivity to any components of these therapies." (PMID 40264573, 2025). "Meta-analyses of randomised controlled trials have demonstrated that pancreatitis events during tirzepatide therapy are rare and not statistically different from rates observed with placebo or insulin comparators." (PMID 41409973, 2025). "In risk assessment phase 1 without biases‐pairing, substantially increased incidence risks of pancreatitis, gastric ulcer, acute nephritis, and leukemia were observed in both short‐term and/or long‐term usage of GLP‐1 RAs when compared with insulin subcutaneous injection group." (PMID 39435881, 2024). "Therefore, the design of connecting the H-2KD binding insulin B chain peptide insulin B chain, amino acid 15-23 (IbsB15-23) to the N-terminal of β2m/CD3-ζ, made the mRNA encoding chimeric MHC-I receptor could target effector CD8 to diabetic CD8+ T cells, which reduced pancreatitis in NOD mice." (PMID 36405706, 2022). "None of the patients in the insulin group received a rescue PE; there were two patients who developed a severe course of pancreatitis after inclusion, but their triglycerides were already <10 mmol/L at 24 h." (PMID 35492338, 2022). "Although infection induced pancreatitis is usually not detected, the possibility of infection induced changes in insulin production cannot be excluded." (PMID 34202952, 2021). "This was assessed in isolated mouse (C57BL/6) pancreatic acinar cells in response to the pancreatitis-inducing agent POA (30 μM) with or without insulin (10 nM) treatment using the pH-Xtra Glycolysis Assay (Agilent)." (PMID 34282152, 2021). "To rule out the effect of insulin on pancreatitis severity, we subcutaneously applied insulin (2 IU/kg, twice daily) after the last cerulein injection until mice were sacrificed." (PMID 33491670, 2021). "Experimental studies on rats have shown that sodium taurocholate-induced pancreatitis did not alter islet morphology or GLUT-2 expression but reduced insulin secretion in response to glucose stimulation, indicating functional deterioration of beta cells." (PMID 34566890, 2021). "Impaired insulin secretion (which occurs in type-1 diabetic Ins2Akita mice) and deletion of IRs in pancreatic acinar cells (which occurs in PACIRKO mice) both led to worse pancreatitis." (PMID 34282152, 2021). "In order to verify that endocrine function in islet cells obtained from pancreatitis patient is not impaired, we compared insulin secretion response to highly concentrated glucose (450 mg/dL) from non-pancreatic patient and pancreatitis patient." (PMID 31311920, 2019). "It is particularly indicated in cases where patients exhibit severe symptoms, such as pancreatitis or hyperviscosity syndrome, which may not respond adequately to insulin therapy alone." (PMID 39958046, 2025). "While insulin is effective, fasting alone can also lower triglyceride levels and may be sufficient in patients without pancreatitis." (PMID 40701175, 2025). "Notably, no disproportionate reporting of “pancreatitis” and “biliary colic” was observed vs. SGLT-2i, while a greater risk was described vs. insulin (ROR 1.58, 95% CI 1.37–1.82, for “pancreatitis”, and ROR 2.40, 95% CI 1.16–4.94, for “biliary colic”)." (PMID 39141075, 2024). "Our results were in line with this characteristic because the pigs that received repetitive cerulein injections and developed pancreatitis did not present any changes in serum insulin over time, nor in serum lipase or amylase activity until the end of the study." (PMID 37175426, 2023). "However, due to non-compliance at home, the patient subsequently developed pancreatitis requiring treatment with an insulin drip." (PMID 37790029, 2023).
pancreatitis (continued). "Therefore, the more severe pancreatitis observed in PACIRKO mice was most likely due to deletion of IRs and the loss of endogenous insulin protection of acinar cells, rather than the non-specifc potentiation of acinar cell injury induced by Cre expression." (PMID 34282152, 2021). "Regarding the digestive panel (including pancreatic insulin profile), several clusters should be specified: firstly, anorexia, nausea, and vomiting may be a consequence of PTH-dependent hypercalcemia, a gastro-duodenal ulcer or pancreatitis, or a connected complaint related to nephrolithiasis." (PMID 38928056, 2024). "Routine vitamin K administration is not recommended in pediatric pancreatitis or DKA guidelines, which focus on fluid, electrolyte, insulin, pain control, and nutritional support." (PMID 41262426, 2025). "Since pancreatitis was more severe in PACIRKO mice lacking acinar cell IRs, we next wanted to investigate the mechanism for the protective effect of insulin on acinar cells from IRlox/lox mice vs PACIRKO mice." (PMID 34282152, 2021). "In the randomized controlled trials reviewed there were no reported cases of pancreatitis in patients treated with the GLP-1 RA and insulin combinations." (PMID 23061470, 2013). "This was achieved using ‘cellular models’ of pancreatitis in which isolated acinar cells (from IRlox/lox vs PACIRKO mice), were pre-treated with or without insulin (10 nM for 15 min) followed by POA to induce cytotoxic Ca2+ overload as a readout of cellular injury." (PMID 34282152, 2021).
Hyperkalemia (145 papers, 2006 to 2026). An abnormally increased potassium concentration in the blood. "Insulin promotes intracellular potassium uptake; thus, insulin deficiency can result in hyperkalemia." (PMID 40705102, 2025). "The pronounced hyperkalemia observed was a consequence of the inhibition of insulin release caused by octreotide." (PMID 39347364, 2024). "For the AV- blocks, some were managed with CPR (16.7%), transvenous pacemakers (75%) and other who had acute reversible cause such hyperkalaemia were manage with administration of calcium gluconate, bicarbonate and insulin (25%)." (PMID 35934708, 2022). "Hyperglycemic patients (serum glucose > 300 mg/dL) can be given insulin alone to avoid worsening hyperkalemia caused by the hyperosmolar state." (PMID 35466190, 2022). "In humans, insulin is used intravenously with dextrose water to treat hyperkalemia, as it causes K+ entry inside the cells." (PMID 32678116, 2020). "IRI also caused hyperkalemia in all groups through acidosis and reduced excretion in the kidneys, and reduced insulin levels due to diminished perfusion of the pancreas." (PMID 32122358, 2020). "We propose insulin–glucose as first-line treatment in patients with relative contraindication to β-2 agonists and patients with severe hyperkalemia (i.e., ≥ 6.0 mmol/L or associated with ECG changes)." (PMID 30820692, 2019). "Additionally, recognition of type 4 RTA as a cause of hyperkalemia in diabetics is essential, as this significantly impacts the use of insulin." (PMID 41146800, 2025). "However, its administration in patients with renal impairment poses a risk of hyperkalemia due to its suppression of insulin-mediated cellular potassium uptake, and it should be used with caution." (PMID 39347364, 2024). "The inhibition of insulin release, which reduces cellular potassium absorption and raises extracellular potassium concentration, is most likely the mechanism underlying octreotide-induced hyperkalemia." (PMID 39347364, 2024). "Hyperkalemia caused by alpha 2 agonists is hypothesized to be induced by the inhibitory effects of the alpha 2-adrenergic receptor on insulin production which can alter the potassium homeostasis." (PMID 39176395, 2024). "Sodium bicarbonate effects may also be influenced by the cause of hyperkalemia and the concomitant administration of insulin." (PMID 39768744, 2024). "The reason for this association is unknown, since patients with hyperkalemia received similar doses of intravenous insulin and had a similar glomerular filtration rate as patients with hypo- or normokalemia (data not shown)." (PMID 38594758, 2024). "Additionally, lab measurement of potassium can be misleading, as initial hyperkalemia due to acidosis and insulin deficiency may mask significant total body potassium depletion, which only becomes evident after insulin therapy and correction of acidosis." (PMID 41141170, 2025). "Fasting hyperkalemia occurs due to the suppression of endogenous insulin secretion during fasting, leading to the shift of potassium from the ICF to the ECF." (PMID 40498214, 2025). "Following identification of the hyperkalemia, the patient was treated with glucose-insulin therapy, intravenous fluids, diuretics, and sodium polystyrene sulfonate, leading to normalization of serum potassium levels." (PMID 40718189, 2025). "For severe hyperkalemia, promptly administer intravenous calcium gluconate, followed by glucose and insulin." (PMID 40705102, 2025). "Plain-language Summary Hyperkalemia, a condition where there is too much potassium in the blood, is often treated with insulin and glucose." (PMID 41660655, 2025). "The therapeutic cornerstone is the prompt correction of hyperkalemia and stabilization of cardiac conduction with intravenous calcium, followed by insulin-dextrose, β2-agonists, and renal replacement therapy when indicated." (PMID 41220480, 2025). "Insulin glucose infusion (IGI) + salbutamol + potassium binders were used for the treatment of severe hyperkalemia." (PMID 40747151, 2025).
Hyperkalemia (continued). "IV fluids were decreased to 100 mL/h, and furosemide, calcium gluconate, D50, insulin lispro, and sodium zirconium cyclosilicate were administered in response to the fluid-overloaded status and hyperkalemia." (PMID 41189717, 2025). "All 76 patients had received intravenous calcium salt and insulin as initial hyperkalemia treatment." (PMID 40290138, 2025). "On day 3, glucose-insulin therapy (500 mL of 10% dextrose with 10 units of insulin) was administered to control hyperkalemia; however, the effect was limited." (PMID 41181722, 2025). "In the present case, hyperkalemia developed on day 4 of hospital stay and was managed with potassium diuresis and insulin-induced intracellular potassium shift." (PMID 41189717, 2025). "BRASH syndrome was suspected in the ED, prompting initiation of treatment with an epinephrine drip and insulin to address the hyperkalemia." (PMID 40786396, 2025). "Her hospital course was complicated by a course of hyperkalemia (serum potassium level was 6.4 mmol/L) and she received standard treatments for hyperkalemia of calcium, insulin, dextrose, and sodium zirconium cyclosilicate." (PMID 40402059, 2025). "There have been case reports of rebound hyperkalemia occurring upon rewarming or after discontinuation of an insulin pump." (PMID 40630352, 2025). "Emergency drugs were kept ready, such as insulin for hyperkalemia, inhaled β2 agonists for hyperkalemia, and furosemide and calcitonin for hypercalcemic crisis." (PMID 40150828, 2025). "Initially, administration of insulin and glucose resulted in a decrease in serum potassium level, although hyperkalemia persisted and even increased over time despite continuous infusion of insulin and glucose." (PMID 40687894, 2025). "Calcium gluconate, sodium zirconium cyclosilicate, regular insulin and 50% dextrose in water were administered for hyperkalemia followed by albuterol nebulization." (PMID 40995280, 2025). "Hyperkalemia was medically treated with D50, regular insulin, sodium zirconium cyclosilicate, albuterol, calcium gluconate, and furosemide, and octreotide was discontinued." (PMID 39347364, 2024). "In the first hour, important treatments were fluid resuscitation with 30 ml/hour of normal saline, insulin infusion at 6 units per hour and standard hyperkalaemia management." (PMID 38616273, 2024). "Because insulin combined with glucose was more frequently administered to patients in the SZC group than to those in the CPS group, an additional analysis, which excluded patients who received insulin with glucose for acute hyperkalemia, was also conducted." (PMID 39553124, 2024). "Refractory ventricular fibrillation persisted for 32 min under resuscitation despite the administration of total calcium chloride of 800 mg, regular insulin of 30 units, and sodium bicarbonate of 170 mEq injection for extreme hyperkalemia management." (PMID 38799756, 2024). "In acute and potentially lethal conditions, hyperkalemia treatments include glucose and insulin, bicarbonate, calcium gluconate, beta-2 agonists, hyperventilation, and dialysis." (PMID 38406030, 2024). "Insulin, a β2-adrenergic agonist, a cation-exchange resin, or a diuretic were used to correct hyperkalemia in 29 cases." (PMID 38985174, 2024). "Several treatments can be used to treat hyperkalemia, including intravenous calcium salts, insulin with glucose, albuterol, and intravenous sodium bicarbonate." (PMID 39768744, 2024). "The administration of membrane-stabilizing drugs, such as intravenous calcium and insulin, should be considered even for mild hyperkalemia, aiming to promote a more effective correction of the electrolyte disturbance." (PMID 39618623, 2024). "Our guideline suggests 10 units of insulin for hyperkalaemia, but we found that ward practices vary." (PMID 38871123, 2024). "Second, the use of insulin with glucose as concurrent therapy for acute hyperkalemia was more common in the SZC group than in the CPS group." (PMID 39553124, 2024).
Hyperkalemia (continued). "Differences before and after entering dialysis were statistically significant for almost all drugs/drug classes, except for Insulin, Vitamin D, and Iron chelating agents/Drugs for the treatment of hyperkalaemia and hyperphosphatemia." (PMID 38493085, 2024). "Clinical guidelines recommend treatment for hyperkalemia should include the administration of intravenous (IV) insulin in doses ranging from 5 to 10 units, along with 25 to 50 g of dextrose." (PMID 39274318, 2024). "By inhibiting insulin, octreotide affects the suppression of the cell membrane Na+/K+ ATPase and a resulting increase in serum potassium, resulting in hyperkalemia." (PMID 39347364, 2024). "Hyperkalemia management included calcium chloride, sodium bicarbonate, furosemide, insulin, salbutamol, kayexalate, and hemodialysis." (PMID 38799756, 2024). "The demographics of the population treated with insulin/dextrose for hyperkalaemia were similar in both time periods." (PMID 38871123, 2024). "Treatment was initiated with isoproterenol to stimulate heart rate, along with fluid therapy, calcium gluconate, and insulin to address hyperkalemia." (PMID 39618623, 2024). "Case 1 involved a 69-year-old male with CKD who underwent total thyroidectomy under general anesthesia and developed intraoperative hyperkalemia, requiring glucose-insulin (GI) therapy." (PMID 39717293, 2024). "There is a need for a more aggressive correction of hyperkalemia, even if mild, with intravenous administration of insulin, glucose, and calcium for membrane stabilization (typically used only in severe hyperkalemia)." (PMID 39618623, 2024). "Treatment options to improve acute hyperkalemia include calcium salt, insulin with glucose, beta-agonists, bicarbonate, loop diuretics, potassium binders, and dialysis." (PMID 39553124, 2024). "Of the 3 patients with severe hyperkalemia, 2 received emergency hemodialysis, and the other was treated with insulin and glucose (40 mL 50% glucose + 5U insulin) intravenous injection after t2." (PMID 39969301, 2024). "In view of these limitations, we recognize that SZC appears to be an effective adjuvant treatment alongside other cornerstone treatments for emergent hyperkalaemia, including insulin–dextrose infusions and sodium bicarbonate." (PMID 39669394, 2024). "Given the presence of severe hyperkalemia with an electrocardiogram (EKG) showing a tall and peaked T wave, the patient received intravenous calcium gluconate and hyperkalemia cocktail containing insulin, albuterol nebulization, and sodium bicarbonate." (PMID 39055480, 2024). "He received treatment according to his ECG presentation, including 400 mg of calcium chloride, 10 units of regular insulin, and 51 mEq of sodium bicarbonate injections, under the impression of hyperkalemia." (PMID 38799756, 2024). "Insulin and glucose were continued throughout the procedure for the management of hyperkalemia with close intra-operative potassium monitoring." (PMID 37660010, 2023). "Hyperkalemia was treated with albuterol, furosemide, insulin and dextrose infusion, and calcium gluconate for cardiac stability." (PMID 37660010, 2023). "Ten units of intravenous (IV) regular insulin with 25 g of glucose is the mainstay for treating hyperkalemia." (PMID 36371171, 2022). "Studies were eligible for inclusion if they reported on any adverse effects in hospitalised patients ≥18-years-old, with hyperkalaemia receiving treatment that included insulin." (PMID 35552566, 2022). "What are the reported adverse effects of insulin therapy during the emergency treatment of hyperkalaemia?" (PMID 35552566, 2022). "Regarding treatment, 12 out of 15 cases required Na supplementation and 2 cases required glucose-insulin therapy to control hyperkalemia." (PMID 36079066, 2022). "Laboratory studies revealed improved hyperkalemia, a persistently high anion gap, and Acidosis despite insulin drip and IV fluid." (PMID 35651382, 2022).